FAM133A (family with sequence similarity 133 member A)
Synonyms: RP1-32F7.2; FLJ37659; CT115
Tractability: PROTAC: ubiquitination databases record sites on it.
Gene: Protein-coding gene on chromosome X (93,673,181 to 93,712,274, forward strand). Ensembl gene ENSG00000179083.
Subcellular location (Human Protein Atlas): Nucleoli; Nucleoplasm
Gene Ontology:
Molecular function: protein binding
Homologues: Orthologues: chimpanzee FAM133A (99% identical), macaque FAM133A (97% identical), dog FAM133A (90% identical), pig FAM133A (90% identical), rabbit FAM133A (88% identical), tropical clawed frog fam133b (62% identical), zebrafish fam133b (50% identical). Paralogues in human: FAM133B (80% identical).
Diseases named in the same sentence as FAM133A in open-access papers:
FAM133A is named in the same sentence as 6 diseases in open-access papers, as found by Europe PMC text mining. Sharing a sentence is not in itself a finding about the gene and the disease. The quoted sentences say what the papers report.
glioma (4 papers, 2020 to 2022). A benign or malignant brain and spinal cord tumor that arises from glial cells (astrocytes, oligodendrocytes, ependymal cells). "FAM133A has been confirmed in previous studies to be related to the invasion and metastasis of glioma." (PMID 34567094, 2021). "While in glioma, FAM133A is the downstream target of miR-155." (PMID 35677036, 2022). "FAM133A was found to be related to glioma invasion and migration." (PMID 34108992, 2021). "The low expression of miR-155 in IDH1-mutant glioma can upregulate the expression of FAM133A, which may further reduce the invasiveness and proliferation of IDH1-mutant glioma by targeting Matrix metalloproteinase-14 (MMP14)." (PMID 35677036, 2022). "The cancer–testis antigen FAM133A is a downstream target of miR-155 and is a negative regulator of glioma invasion and migration." (PMID 33193574, 2020).
cervical cancer (1 paper, 2022). A primary or metastatic malignant neoplasm involving the cervix. "High expression of FAM133A in cervical cancer and pancreatic cancer has been reported to be associated with the malignant degree of tumors." (PMID 35677036, 2022).
tumor (5 papers, 2020 to 2022). "Co-expression networks were constructed based on 461 genes significantly associated with driver genes and the hub gene FAM133A in the network was identified to be associated with tumor metastasis." (PMID 34567094, 2021). "In contrast to the driver gene FAM133A, the driver gene SORCS3, in combination with its co-expressed genes, plays an important role in tumor metastasis, hypoxia and apoptosis." (PMID 34567094, 2021). "Based on our network and the ceRNA mechanism, we speculated that LINC01128 might act as a tumor suppressor in MM through multiple mechanisms, including miR-142-5p/PARP9 or FAM133A axis, and the miR-299-3p/estrogen-related receptor gamma axis." (PMID 33193574, 2020). "The results showed that tumor cells from nonmetastatic tumors expressed high levels of MMP1, KRT1, and MMP13 and low levels of MGST1, FAM133A, and FMO3." (PMID 36569924, 2022).
cancer (1 paper, 2022). A tumor composed of atypical neoplastic, often pleomorphic cells that invade other tissues. "FAM133A is a type of Cancer-Testis Antigen (CTA), a class of proteins that is highly expressed in immune privilege sites such as the brain and testis." (PMID 35677036, 2022).
FAM133A also shares sentences with these, for which no sentence is quoted: Intellectual disability (1 paper); pancreatic cancer (1).